INS (insulin)
Diseases named in the same sentence as INS in open-access papers (continued):
Sharing a sentence is not in itself a finding about the gene and the disease.
metabolic syndrome (continued). "These alterations found in obese people are best summarised by the metabolic syndrome, mainly characterized by high serum levels of glucose, insulin and triglycerides, as well as a chaotic pattern of cytokines." (PMID 21179032, 2011). "The non-diabetic middle-aged offspring had a lower prevalence of metabolic syndrome, lower mean fasting blood glucose and insulin levels, a higher mean insulin sensitivity and a more favourable glucose tolerance than their partners." (PMID 21115528, 2011). "A healthy diet also reduces insulin secretion and increases insulin sensitivity and prevents the occurrence of metabolic syndrome, and also DM2 in people with impaired glucose tolerance, both of which impair cognitive performance." (PMID 21568932, 2011). "Of various categories of metabolic syndrome, high waist circumference, high triglycerides, and high fasting plasma glucose showed a significantly higher prevalence in the insulin-resistant subjects in both genders." (PMID 22025967, 2011). "Restriction of dietary CHOs would counteract this signalling cascade by normalizing glucose and insulin levels in subjects with metabolic syndrome, in this way acting similar to calorie restriction/fasting." (PMID 22029671, 2011). "Compared to Caucasian populations, South Asians typically develop metabolic syndromes at lower BMIs, and are known to have increased visceral fat and insulin resistance." (PMID 21276235, 2011). "The gene-activators increase glucose disposal rate and insulin sensitivity and, by restoring normal glucose and insulin levels, remove metabolic syndrome and DM2." (PMID 21568932, 2011). "Prevalence of metabolic syndrome was significantly higher in insulin-resistant subjects in both men (29.3% vs. 10.3%) and women (34.1% vs. 15.6%)." (PMID 22025967, 2011). "The gene-activators regress atherosclerosis, by normalization blood glucose – insulin homeostasis remove metabolic syndrome and DM2, and prevent cognitive decline and dementia." (PMID 21568932, 2011). "In fructose-fed rats, Hypericum normalised the dyslipidemia induced by fructose feeding and improved the insulin sensitivity." (PMID 22084716, 2011). "Beneficial effects of add-on therapy with pioglitazone to intensive insulin therapy on dyslipidemia were reported for patients with HbA1C > 8% at baseline." (PMID 21756323, 2011). "Compared with Caucasian populations, AIs typically develop metabolic syndromes at lower BMIs, and for any given waist circumference, have increased visceral fat and insulin resistance, but thinner extremities." (PMID 21619649, 2011). "Our study demonstrates that raw garlic homogenate is effective in improving insulin sensitivity while attenuating metabolic syndrome and oxidative stress in fructose-fed rats." (PMID 21794123, 2011). "They prevent and regress atherosclerosis and, by restoring normal glucose-insulin homeostasis, remove metabolic syndrome and DM2." (PMID 21568932, 2011). "The biological mechanism through which physical activity affects metabolic syndrome, for example, via increasing insulin sensitivity and improving endothelial function, should not differentiate among primarily middle-aged men and women." (PMID 21159230, 2011). "These women had improvements in insulin sensitivity, dyslipidemia, ovulatory patterns, and adiposity indices as a consequence of the addition of metformin-flutamide to a regimen of OCP monotherapy." (PMID 21899727, 2011). "In contrast, it has been shown that an excessive induction of SOCS1 by TLR ligands and cytokines contributes to the alteration of insulin sensitivity in metabolic syndrome." (PMID 20862390, 2010). "This phytonutrient combination provides a potential therapy for correcting or modulating dysregulated lipids and improving insulin sensitivity in metabolic syndrome." (PMID 20721358, 2010).
metabolic syndrome (continued). "The metabolic syndrome components (e.g., abdominal obesity, triglycerides, insulin, HDL-cholesterol, inflammatory markers, etc.)and criteria (e.g., cut-points used to define high-risk values) employed in these studies varied considerably." (PMID 20459784, 2010). "Many of our linkage signals were linked to chromosomal regions observed by other genome scans for hypertension, fasting insulin, dyslipidemia, visceral fat area and/or low metabolic rates." (PMID 20181263, 2010). "In both groups, B and C, frequent exercise improved dyslipidemia and reduced insulin requirements significantly (P = 0.00 both), as well as a reduction in BMI (P = 0.05, P = 0.00 respectively) and waist circumference(P = 0.02, P = 0.00 respectively)." (PMID 20618996, 2010). "A range of different compounds and plant food extracts studied show various activities relevant for insulin secretion, and the activities are different on normoglycaemic controls and the subjects with symptoms of metabolic syndrome." (PMID 20480025, 2010). "We investigated their effects on triglyceride (TG) deposition in 3T3-L1 adipocytes, glucose and insulin in obese mouse models, and metabolic syndrome markers in adults with metabolic syndrome." (PMID 20721358, 2010). "Liver fat percent correlates with insulin sensitivity and all components of the metabolic syndrome except for hypertension." (PMID 20553596, 2010). "As a real example, PCBMR was applied to test association in a study of traits-weight, waist circumference, BMI, hip circumference, plasma insulin, and insulin-glucose ratios-of abdominal obesity-metabolic syndrome in the Bogalusa Heart Study cohort." (PMID 21062472, 2010). "Beneficial results with this ratio of actives on serum glucose and insulin in two diabetic mice models led us to conduct a 12-week clinical trial in individuals with the metabolic syndrome." (PMID 20721358, 2010). "Clinical repercussions of the metabolic syndrome include alterations in glucose and lipid homeostasis of which insensitivity to the actions of insulin is a key feature." (PMID 22615610, 2010). "In 2007 McGoldrick reviewed randomized trials of statins, fibrates, and insulin-sensitizers for managing dyslipidemias in HIV-infected subjects taking ART." (PMID 20573187, 2010). "Metabolic syndrome (MetS) is a cluster of various clinical cardiovascular risk factors including obesity, dyslipidemia and hypertension, and is characterized by high fasting circulating insulin levels." (PMID 20809949, 2010). "Body fat is related to changes in lipid profile, blood pressure and metabolism of insulin and glucose, known as the metabolic syndrome (MS)." (PMID 20537155, 2010). "Two recent small studies, however, found reduced insulin levels in patients with metabolic syndrome and diabetes after nut feeding." (PMID 22254047, 2010). "After six months, the treatment proved to be effective in reducing insulin and lipid levels and in ameliorating the complications of metabolic syndrome." (PMID 21274310, 2009). "Fibrates are used to treat dyslipidemia mainly for its ability to stimulate fatty acid oxidation, while TZDs are used to improve insulin sensitivity and glucose homeostasis." (PMID 19636418, 2009). "The trial examines participant weight loss and dietary quality as well as changes in components of the metabolic syndrome, inflammatory biomarkers, low-density lipoprotein cholesterol levels, insulin levels, and glycosolated hemoglobin." (PMID 20042092, 2009). "After 12–13 weeks on cafeteria diet, C57BL/6 mice had a phenotype of higher body weight, serum glucose and insulin, dyslipidemia, and had higher serum TNFα and similar IL-6 compared to normal diet controls." (PMID 18474108, 2008). "In this study, men with hypogonadal testosterone levels were twice as insulin resistant as their eugonadal counterparts, and 90% fulfilled criteria for the metabolic syndrome." (PMID 18266714, 2008).
metabolic syndrome (continued). "This study confirms that reducing dietary carbohydrates produces improvements in characteristics of dyslipidemia and insulin sensitivity." (PMID 18990242, 2008). "BMI, waist-hip ratio, diastolic blood pressure, ALT, HDL-cholesterol, fasting plasma glucose and insulin C-peptide showed deviations typically seen in the metabolic syndrome." (PMID 18958176, 2008). "Carbohydrate restricted diets (CRD) consistently lower glucose and insulin levels and improve atherogenic dyslipidemia [decreasing triglycerides and increasing HDL cholesterol (HDL-C)]." (PMID 18289377, 2008). "CRDs are ideal for reducing inflammation because they reduce plasma glucose excursions, the major stimulus for pancreatic secretion of insulin, and modulate the underlying factors associated with CVD and the metabolic syndrome." (PMID 18289377, 2008). "Chemically synthesized ligands for nuclear receptors of the PPAR family modulate a number of physiological functions, particularly insulin resistance in the context of energy homeostasis and the metabolic syndrome." (PMID 18645617, 2008). "In contrast, drugs that target PPARγ appear, at least intheory, to offer an attractive and perhaps more logical approachto treating the metabolic syndrome, by virtue of their ability toameliorate insulin resistance and other facets of the condition." (PMID 17389771, 2007). "In view of these results, we wished to assess in which metabolic variables the surplus subjects, differed from subjects free of the metabolic syndrome or from subjects identified by an insulin measurement requiring definition." (PMID 18088443, 2007). "Metabolic syndrome components would likely tend to cluster more in individuals with large weight gain on a physiologic basis characterized by high fasting insulin concentration." (PMID 17827860, 2007). "In metabolic syndrome, the body becomes resistant to insulin, and high levels of glucose remain trapped in the blood." (PMID 16948861, 2006). "Generally speaking the treatments available for metabolic syndrome are based in both life style modification (dietary advice and advice to increase physical activity) and medical treatment to enhance insulin sensitivity." (PMID 17101046, 2006). "In this way, elevated TAG resulting from disruption in insulin function, plays a central role in regulating the atherogenic dyslipidemia of MetS." (PMID 16288655, 2005). "Fructose induced insulin resistant states are commonly characterized by a profound metabolic dyslipidemia, which appears to result from hepatic and intestinal overproduction of atherogenic lipoprotein particles." (PMID 15723702, 2005). "The males and females who developed GI had hallmarks of the metabolic syndrome such as concomitant increases in body mass index, blood pressures, triglycerides, serum insulin, and fasting glucose." (PMID 14604220, 2003). "Future research should focus on insulin resistance mechanisms, metabolic syndrome management, and the optimization of assisted reproductive technologies including frozen embryo transfer, letrozole combination therapies, and traditional Chinese medicine approaches." (PMID 42221129, 2026). "The findings indicate that AYN may have the potential to alleviate dyslipidemia associated with T2DM, thereby contributing to the improvement of insulin sensitivity and the reduction of blood glucose levels." (PMID 41509193, 2026). "Inflammatory mediators and reactive oxygen species resulting from insulin resistance, visceral adiposity, and dyslipidemia may contribute to retinal ganglion cell apoptosis and optic nerve degeneration." (PMID 41399378, 2026). "Key learning points include the role of gut microbiota in lipid metabolism, insulin sensitivity, and systemic inflammation, and how targeted microbiome interventions could represent novel strategies for mitigating metabolic syndrome." (PMID 40901177, 2025).
metabolic syndrome (continued). "However, in a rat model of metabolic syndrome, dietary supplementation with PI reduced hepatic steatosis, improved insulin levels, and decreased liver inflammation." (PMID 41002958, 2025). "Dietary interventions targeting whole, minimally processed, plant-based foods, lean proteins, and healthy fats demonstrate potential for preventing, delaying, or reversing metabolic abnormalities such as impaired insulin function, dyslipidemia, and chronic inflammation." (PMID 41003008, 2025). "Similarly, the co-administration of resveratrol and omega-3 fatty acids has been shown to improve insulin sensitivity and decrease systemic inflammation in metabolic syndrome by modulating key signaling pathways like NF-κB and MAPK." (PMID 41002745, 2025). "Moreover, Zumba training increases insulin sensitivity and optimises glucose regulation, which is crucial for preventing metabolic syndrome and improving overall metabolic health." (PMID 40868873, 2025). "In turn, androgen receptor-knockout mice exposed to a high-fat diet were found to be characterized by the earlier development of atherosclerotic changes in the aorta, impaired insulin sensitivity, and atherogenic dyslipidemia in comparison to control mice with the intact androgen receptor gene." (PMID 40290009, 2025). "Furthermore, insulin sensitivity and metabolic syndrome scores improved substantially compared to controls." (PMID 40699839, 2025). "Additionally, differences in the gut microbiota composition among populations impact the effectiveness of fecal microbiota transplantation in improving the insulin sensitivity of patients with metabolic syndrome." (PMID 40027477, 2025). "Furthermore, circadian misalignment impairs glucose metabolism and insulin sensitivity, contributing to insulin resistance while also affecting lipid metabolism, leading to dyslipidemia." (PMID 40142186, 2025). "Restoration of insulin concentration may correct those abnormalities in lipid metabolisms in diabetic rats, further explaining how AE managed to normalize dyslipidemia in diabetic rats." (PMID 40448078, 2025). "However, adding arsenic to the HFD regimen reduced fasting glucose, fasting insulin, insulin resistance and tolerance, β-cell function, dyslipidemia, and islet insulin secretion." (PMID 40726918, 2025). "The blood samples from the DHFU group had a milky appearance with significantly elevated serum uric acid, Glu, TG and TC levels, and decreased insulin levels, indicating the successful establishment of a diabetic hamster model with hyperuricemia and dyslipidemia." (PMID 41012372, 2025). "The prevalence of dyslipidemias is higher in donkeys (10–20%) than in horses and ponies, which is more evident in obese, pregnant, lactating, and older animals, perhaps because of the reduced insulin sensitivity." (PMID 40362152, 2025). "In addition, Berberine exerts hepatoprotective effects by inhibiting lipogenesis and gluconeogenesis while improving insulin sensitivity and lipid profiles.Ginsenoside Rb1 demonstrates significant improvements in dyslipidemia." (PMID 41001340, 2025). "Physical activity increases insulin sensitivity and reduces the risk of metabolic syndrome, regardless of changes in BMI." (PMID 41479473, 2025). "Oxidative stress impairs insulin signaling and promotes metabolic syndrome." (PMID 40427413, 2025). "Another study found that insomnia symptoms with major depression may be associated with higher body mass index and waist circumference and lower levels of metabolic syndrome components, triglycerides, insulin, and albumin." (PMID 40427032, 2025). "Insulin is essential for regulating lipid metabolism and mitigating dyslipidemia in diabetic rats." (PMID 40448078, 2025). "Indeed, the interplay between dyslipidemia and various metabolic disturbances is multifaceted, involving systemic inflammation, oxidative stress and insulin resistance, which collectively contribute to increased cardiometabolic risk." (PMID 40077646, 2025).
metabolic syndrome (continued). "In conclusion, this systematic review and meta-analysis provide robust preclinical evidence supporting the beneficial effects of kefir on weight management, lipid modulation, and insulin regulation, as well as the reduction of oxidative stress and inflammation in rodent models of metabolic syndrome." (PMID 40565686, 2025). "Physiologically, this may reflect dyslipidemia, elevated triglycerides, and increased insulin concentrations, all common among individuals with higher BMI and fat mass." (PMID 41312189, 2025). "The method by which metabolic syndrome impacts lung function could be related to increases in pro-inflammatory cytokines, with contributions from elevated insulin, dyslipidemia, and leptin." (PMID 39714726, 2025). "Importantly, curcumin’s anti-inflammatory, antioxidant, and insulin-sensitizing properties align well with the pathophysiological mechanisms of metabolic syndrome." (PMID 40868165, 2025). "Similarly, metabolic syndrome patients adhering to an 8:00–16:00 feeding window exhibited a 57% increase in ketogenesis and insulin sensitivity, both critical for post-stroke metabolic resilience." (PMID 41184254, 2025). "We observe that oral exposure to deltamethrin resulted in significant modulation of insulin response and lipid metabolism in the liver, in line with our prior report and highlighting impacts to metabolism that may shape metabolic syndrome." (PMID 40894792, 2025). "Prevailing metabolic derangement in GDM (either with or without metabolic syndrome)—reduced insulin sensitivity with inappropriate insulin response—does not cause purely carbohydrate metabolism disturbances, but affects other nutrients too incl." (PMID 40649117, 2025). "Increasing magnesium intake through diet or supplements can significantly improve various metabolic abnormalities in metabolic syndrome patients, including enhanced insulin sensitivity, healthier glucose control (fasting & after meals), better lipid readings, and regulated blood pressure." (PMID 41245414, 2025). "In experimental animal models, it has shown potential in inhibiting metabolic syndrome, helping to control blood glucose levels and body weight by improving insulin sensitivity and reducing fat accumulation, thus mitigating the progression of metabolic syndrome (A. and I., 2017)." (PMID 40110027, 2025). "We aimed to assess whether reducing sedentary behaviour in patients with metabolic syndrome impacts renal glucose uptake rate (GU) during insulin stimulation." (PMID 40692323, 2025). "Short-term interventions with strict carbohydrate restriction may rapidly improve insulin sensitivity and dyslipidemia by leveraging ketosis-driven appetite suppression and increased energy expenditure." (PMID 40933261, 2025). "Furthermore, natural phosphorus sources contribute to better cholesterol metabolism, improved insulin sensitivity, and reduced vascular inflammation, which can benefit individuals with hypertension or metabolic syndrome." (PMID 40070480, 2025). "Additionally, the sympathetic nervous system—invariably upregulated in metabolic syndrome—can inhibit insulin secretion via adrenergic receptors on β-cells." (PMID 40871736, 2025). "The review highlights how exercise-induced modulation of FoxO pathways contributes to improved insulin sensitivity, muscle hypertrophy, cardiovascular health, neuroprotection, and reduced risks of chronic diseases, including metabolic syndrome, neurodegeneration, cardiovascular disease, and cancer." (PMID 40861274, 2025). "The improvement of DASH diet on insulin sensitivity and metabolic syndrome may further promote the recovery of vascular endothelial function, thereby improving arterial elasticity." (PMID 41229546, 2025). "Furthermore, all major pathological contributors are integral to Alzheimer's disease pathogenesis as inflammation, oxidative stress, dyslipidemia, and insulin resistance." (PMID 40979532, 2025).